CD24 (CD24 molecule)
Diseases named in the same sentence as CD24 in open-access papers (continued):
Sharing a sentence is not in itself a finding about the gene and the disease.
breast cancer (continued). "Notably, in breast cancer, the absence of CD24 combined with the presence of CD44 and EpCAM (CD24−CD44+EpCAM+) appears to be critical for the identification of breast CSCs." (PMID 24955581, 2014). "However, CD44+/CD24-/low/ESA+ is not a universal marker phenotype of TICs in all breast cancer subtypes." (PMID 25216750, 2014). "In an attempt to identify novel antigens that may be combined with CD44 and CD24 to specifically sort TICs, we compared the expression of a panel of surface antigens between the CD44+/CD24-/low and CD44+/CD24+ cell subpopulations of three basal A or B breast cancer cell lines." (PMID 25216750, 2014). "In an attempt to isolate and understand tumorigenic from non-tumorigenic breast cancer cells, Al-Hajj and colleagues used antibodies against CD24 (Heat stable antigen/HAS/BA-1) and CD44 (H-CAM/Pgp-1) to separate heterogeneous cell types in patient-derived xenografts grown in immune-compromised mice." (PMID 25080108, 2014). "The first solid tumour stem cells were identified in breast cancer, where it was demonstrated that a CD44+CD24- marker-bearing subpopulation could regenerate a tumour from as little as 100 cells, whereas tens of thousands of cells from the bulk population failed to do so." (PMID 23631621, 2013). "CD49f and SSEA4 along with other surface markers, such as CD24, CD44, CD133, have been commonly used for the detection of CSCs in solid tumors, including human breast, brain, colon, and ovarian cancer, as well as for categorizing breast cancer molecular subtypes." (PMID 23761858, 2013). "Furthermore, the presence of CD24−/CD44+ or CD24+/CD44+ cells in primary tumors did not correlate with the overall or metastasis-free survival of breast cancer patients." (PMID 23042145, 2012). "Similarly, in human breast cancers, tumor suppressor miRNA let-7 which inhibits self-renewal capacity and promotes differentiation by repressing H-Ras and high mobility group AT-hook 2 (HMGA2)was found to be downregulated in the CD44+/CD24−/low BCSCs." (PMID 24977105, 2012). "Because the significance of CD44+/CD24- is probably not unique to breast cancer, and CD44 has been highly expressed in gastric cancer, we might speculate that similar or other molecules may also regulate the process of recurrence for gastric cancer." (PMID 22839505, 2012). "However, in samples from patients with tumor recurrence or metastasis, the proportion of CD44+/CD24- tumor cells was significantly higher in breast cancer tissue with basal-like features than in tissue without such features (22.66% versus 17.70%, p = 0.05)." (PMID 22762532, 2012). "Moreover, breast cancer stem cells are characterized by the low or negative expression of CD24 but the high expression of CD44." (PMID 23300877, 2012). "We and other groups have found that CD24 is not a consistent breast cancer stem cell marker." (PMID 21317983, 2011). "Hence, while the CIC enriched subset may be isolated from breast cancer cell lines by the CD markers CD44 and CD24, ALDH, or membrane labeling dye PKH26, obtaining pure cancer stem cell subsets remains a challenge in methodology." (PMID 21935375, 2011). "While, the proportion of CD44+/CD24- cells did not correlate with gene expression-based classifiers of breast cancer subtype, consistent with previous reports, there was a striking relationship between the proportion of CD44+/CD24- cells in the line and spindle-cell morphology." (PMID 20964822, 2010). "However, the possibility that SLUG participates in CD44/CD24 phenotypic changes has not been investigated, although its upregulation in basal breast cancers and mammospheres has been reported recently." (PMID 20691079, 2010). "In 2003, Clarke and colleagues demonstrated that a highly tumorigenic subpopulation of BCSCs, expressing CD44+CD24- surface marker in clinical specimen, had the capacity to form tumors with as few as one hundred cells, whereas tens of thousands of the bulk breast cancer cells did not." (PMID 20569497, 2010).
breast cancer (continued). "Notably, a very recent study has shown that cytotoxic chemotherapies including an anthracycline and taxane increased the proportion of ALDH1-positive breast cancer cells but not that of CD44+/CD24- breast cancer cells." (PMID 20959018, 2010). "In contrast to CD44 expression, not all breast cancer cell lines contained CD24+ cells." (PMID 20964822, 2010). "Since the majority of breast cancer cell lines failed to maintain EpCAM+/CD24+/CD49f- Luminal 1 cells in vitro, we wanted to determine whether this was a general feature of in vitro cell cultivation or was a consequence of malignancy." (PMID 20964822, 2010). "Not all basal-like tumors and very few HER2+ tumors, however, contain CD44+/CD24- cells, emphasizing that a putative tumorigenic ability may not be confined to cells of this phenotype and that other breast cancer stem cell markers remain to be identified." (PMID 18559090, 2008). "Furthermore, early cancer cells detected in bone marrow of breast cancer patients were observed to have breast cancer stem sell phenotype, but the frequency of CD44+/CD24-/low cells in breast cancer tissue was not correlated with clinical outcome." (PMID 18433506, 2008). "We found that the CD44+/CD24- status was associated with low/negative HER2 expression and with elevated expression of CK5/14 and EGFR, as well as with medullary histological type, all known characteristics of the basal-like subtype of breast cancer." (PMID 18559090, 2008). "Based on our results, using breast cancer cell lines to target CD44+/CD24-/ESA+ cells for drug discovery offers a highly promising, reproducible, and cost-effective means to identify therapies that prevent self-renewal or force depletion of tumorigenic breast cancer stem-like cells." (PMID 18366788, 2008). "As there exists two distinct populations of CSCs in breast cancer, when reviewing the literature for the potential role of prostaglandin signaling in breast CSC phenotypes it is important to define how the CSCs were identified since there may be a CD44+/CD24- or ALDH+ specific effect." (PMID 35127497, 2021). "In addition, interestingly, we found a higher population of CD24−/low/CD44+ cells among RT-R-TNBC cells than among TNBC cells, and RT-R-TNBC cells showed more aggressive tumorigenic properties related to tumor cell growth, migration and invasion than the parental breast cancer cells." (PMID 34502547, 2021). "To further validate the clinical utility of iSUF, we have processed serum samples from 10 metastatic breast cancer (BC) patients and demonstrated the presence of HER2, CD24 and miR21 biomarkers at significantly higher levels compared to healthy controls (p < 0.05)." (PMID 33850163, 2021). "The fact that mannosidase activity is a prerequisite for formation of complex type N-glycans, which comprise sugars necessary for the function of peripheral CD24, could explain the observation that CD24 had no prognostic influence in tumors with low mannosidase expression in breast cancer patients." (PMID 34360932, 2021). "However, the results have shown that cisplatin more specifically targeted progenitor cells, rather than the stem breast cancer cells, with the reduction of the population of CD24−/CD44+ and ALDH1A1 MDA-MB-231 cells being at higher folds in tpMDA, compared to tsMDA." (PMID 33919109, 2021). "Interestingly, low expression or lack of expression of the CD24 protein has long been considered a marker of breast cancer stem cells, and various clinical trials are underway to target the cancer stem cell population in breast cancer." (PMID 31488082, 2019). "However, the later published evidence that the two breast cancer CSC populations (i.e., ALDH+ and CD24−/CD44+) investigated reside in different areas of primary breast tumors and can transition from one phenotype to the other might affect the reliability of CSC counts in this patient population." (PMID 30788286, 2019).
breast cancer (continued). "However, the clinical impact of CD24 and CD44 expression in tumours remains unclear, and further investigation will be necessary to evaluate the correlation between ER expression and CD44+/CD24− cells in breast cancer." (PMID 29986702, 2018). "Recent studies suggest that CD24 may be a negative tumor propagating marker within breast cancers." (PMID 27276062, 2016). "We found that mice negative or positive for CD24 did not significantly differ in terms of tumor initiation and burden in the genetic tumor models tested, with the exception of Apc1572T/+ mice, in which lack of CD24 reduced the mammary tumor burden slightly but significantly." (PMID 26978528, 2016). "To identify whether flubendazole inhibits breast cancer stem-like cells, we performed flow cytometry analysis to analyze the proportion of CS-like cell subpopulation in breast cancer cells based on the expression of CD44 and CD24 (CD44high/CD24lowconfiguration)." (PMID 25811972, 2015). "In addition, in the breast carcinomas, how to understand why the RP215-recognized IgG mainly correlated with the basal-like-origin of MDA-MB-231 of BCSC that show CD44+/CD24−/low, but not with the luminal-like breast cancer cell line MCF-7 of BCSC as well as the CD133+ or ALDH1+ BCSC." (PMID 26472025, 2015). "However, several markers, including CD133, CD24, CD44, CD166, EpCAM (CD326), CXCR4 (CD184), c-kit (CD117), and among others have been identified as surface markers of CSCs isolated from glioblastoma, breast cancer, pancreatic cancer, prostate cancer, or hepatocellular carcinoma." (PMID 24675390, 2014). "Although there remains a need to determine whether CD44+/CD24-/low cells are true breast cancer stem cells across all the various breast cancer subtypes, there seems to be a connection between EMT and CD44/CD24 expression in the mechanisms of breast cancer invasion and metastasis." (PMID 20696077, 2010). "In breast cancer (BC), a CD44+/CD24–low/Lin− cell population was first identified as T-ICs." (PMID 20145614, 2010). "Because the percentage of CD44+/CD24- cells in breast cancer cell lines does not predict tumorigenic potential, we next considered whether adding ESA to the repertoire of cell surface markers could enrich for tumor initiation capacity, as was previously demonstrated." (PMID 18366788, 2008). "Several techniques have been proposed to isolate or enrich for tumorigenic breast cancer stem cells, including (a) culture of cells in non-adherent non-differentiating conditions to form mammospheres and (b) sorting of the cells by their surface phenotype (expression of CD24 and CD44)." (PMID 18541018, 2008). "Further studies demonstrated that an Os (II) complex with a dca ligand also eradicated CSCs in MCF-7 and SKBR-3 human breast cancer cells, targeting CD44-positive, CD24-negative CSC-like cells and inhibiting mammosphere formation." (PMID 40733139, 2025). "A study found that a cell population isolated from malignant human breast cancer-derived pleural effusions was detected with high expression of CD44 and low or no expression of CD24 (CD44+CD24−/low)." (PMID 37237509, 2023). "In agreement with previous data, the proportions of CD44+CD24- and ALDH1+ breast CSCs were dramatically increased among breast cancer cells cocultured with CCL18-activated NBFs but not with treatment-naive or TGF-β-treated NBFs." (PMID 36418470, 2023). "Analyzing the expression of breast cancer stem cell markers CD44 and CD24, we found that over 95% of control MDA-MB-231 cells express CD44 but not CD24, thus exhibiting a breast cancer stem-like cell phenotype." (PMID 34725457, 2021). "The major characteristic of CSCs in breast cancer is that they express high CD44 levels and low/none CD24 levels and thus are identified as CD44high/CD24low/-cells." (PMID 34072893, 2021).
breast cancer (continued). "Thus, the dormant CD44-/CD24- breast cancer cells that have previously been colonized in the metastatic site may be able to spontaneously convert into CD44+/CD24- breast CSCs to regain their potent proliferative ability and drug resistance, resulting in delayed breast cancer metastasis." (PMID 34318746, 2021). "In the estrogen receptor- and progesterone negative breast cancer cell line MDA-MB-231, the only significantly detected gene expression change was upregulation of the differentiation marker CD24." (PMID 34356204, 2021). "Serum from a cohort of clinical samples from metastatic breast cancer (BC) patients and healthy donors were processed by the iSUF platform and the isolated EVs from patients showed significantly higher expression levels of BC biomarkers (i.e., HER2, CD24, and miR21)." (PMID 33850163, 2021). "The stem-like population of cells in breast cancer is characterised by high expression of CD44 and low or no expression of CD24 (CD44+/CD24-)." (PMID 34863149, 2021). "In agreement, tissues from breast cancer patients of triple-negative breast cancer (TNBC), the most aggressive form of breast cancer, showed CD44+, CD24–, and high ALDH1 phenotype compared to the nonTNBC tissues." (PMID 32391048, 2020). "We indicated that the CC50 value of andrographolide in BCSCs is significantly higher than that in non-BCSCs such as human CD24-/CD44- breast cancer cells and human MCF-7 breast cancer cells." (PMID 33211707, 2020). "In order to further evaluate in vivo the impact of P2Et in BCSC-enriched breast cancer models (triple negative and luminal), we analyzed the expression of CD44, CD24, EpCAM, CD49f and ALDH in human cell lines." (PMID 33184339, 2020). "Data from over 100 breast cancer patients who underwent neoadjuvant chemotherapy with paclitaxel and epirubicin suggest that ALDH1+ cells, but not CD44+CD24− cells, contribute to resistance against chemotherapy." (PMID 30733805, 2019). "Unlike in breast cancers, we identified a significant overlap between the ALDH+ and CD44+CD24− populations, with substantial interindividual variation in the degree of overlap." (PMID 29606612, 2018). "Although it is accepted that HER2-targeted therapy does not respond to HER2-negative breast cancer cells, our data indicated that trastuzumab treatment sensitized the radioresistant phenotype of CD44+/CD24–/low MCF7 cells." (PMID 29464036, 2018). "Our previous investigation of benign mammary stroma indicated that low presence of ALDH1+ CD44+ CD24– r/o cells in premenopausal women is marginally correlated with a family history of breast cancer, but that this does not apply to ALDH1+ CD44– CD24– cells." (PMID 29486751, 2018). "We observed the expression of CD44, CD24 and ALDH1 in both the primary tumor and the metastases, indicating that these markers did not disappear during the development and metastasis of breast cancer." (PMID 29062075, 2017). "Here we found that the CD44/CD24 ratio and the expression of ALDH1 were not consistent in the breast cancer, suggesting their different origins and properties." (PMID 29062075, 2017). "For example, the low or absent expression of CD24, in combination with high CD44, marks breast cancer stem cells." (PMID 28320418, 2017). "In breast carcinoma CD44 positive and CD24 negative cells have been found in distant metastasis, therefore this phenotype is connected with a relapse after surgical resection." (PMID 28758908, 2017). "Furthermore, we also investigated the stimulatory effects of CoCl2 exposure on the BCSC sphere formation, the size of the CD44+/CD24– subpopulation, and the expression of HIF1α and HIF2α with or without HIF2α inhibitor 76 treatment in other liable human breast cancer cell lines such as MDA-MB-231." (PMID 27270657, 2016). "Using 51 different breast cancer cell lines, we found that TNBC cell lines exhibit higher expression of the cancer stem cell surface marker CD44 and lower expression of the non-CSC CD24 compared with other subtypes." (PMID 27759034, 2016).
breast cancer (continued). "Breast cancer stem cells are classically defined by CD44 (Cluster of Differentiation antigen-44) positive and low or absent levels of CD24 (Cluster of Differentiation antigen-24) expression (CD44+/CD24−/low)." (PMID 27876836, 2016). "As CD44+/CD24−/low is the classic stem cell marker in breast cancer, and approximately 99% of MDA-MB-231 cells are CD44+, we focused on the level of CD24 in MDA-MB-231 cells with or without NOP14 overexpression." (PMID 26213846, 2015). "Specific cell surface markers for CSCs have been detected in human mammary neoplasms which stain positive for CD44 and negative or low for CD24." (PMID 24119896, 2013). "When used to evaluate tumor initiation of common breast carcinoma cell lines, the percentage of CD44+/CD24- did not correlate to tumorigenicity, it does, however, correlate strongly with rare basal and mesenchymal phenotype." (PMID 24124614, 2013). "When the Lin-CD24+CD29lo population is further analyzed for CD61 expression, we find that these mammary tumors do not appear to express CD61." (PMID 22992387, 2012). "In breast cancer, the in vivo inoculation of low cell numbers of CD24−/CD44+ but not CD24+/CD44+ or ESA-purified cells from primary tumors gave rise to xenograft tumors." (PMID 23042145, 2012). "Analysis of CD24 and CD29 surface-marker expression on the lineage-negative population of NOTCH1 mammary tumor cells revealed expression of a luminal cell profile (Lin-CD24+CD29lo), compared with wild-type mammary cells." (PMID 22992387, 2012). "For this reason, MCF-7 cells have primarily been used as model of the luminal breast cancer cell type, which express CK8/18, CK19, CD24 and the estrogen receptor, but not vimentin." (PMID 18433506, 2008). "In our studies, the cell lines derived from the original 0_A1 mammary tumor, but not cell lines from posterior tumors contained a population of CD44+/CD24-/low cells." (PMID 18394172, 2008). "Collectively, these data suggest that, analogous to primary breast cancers, a basal cellular phenotype rather than tumorigenicity consistently correlates with the percentage of CD44+/CD24- cells in cell lines." (PMID 18366788, 2008). "Cell lines derived from individual Brca1 mouse mammary tumors had distinct and non-overlapping populations of putative cancer stem cell markers CD44+/CD24- and CD133+." (PMID 18241344, 2008). "CD44+/CD24-/Lin- cells from primary breast cancers progress to CD44+/CD24+, CD44-/CD24+, and CD44-/CD24- phenotypes when implanted into mammary fat pad of nonobese diabetic/severe combined immunodeficiency mice." (PMID 17062128, 2006). "In addition, analysis of the GEO database for breast cancer patients showed a positive correlation between GPR110 expression and CD44 gene and a negative correlation between GPR110 expression and CD24 gene." (PMID 35614051, 2022). "CD44+/CD24− has been widely used as BCSC surface markers, thus we sorted CD44+/CD24− subpopulation (termed as BCSCs) from various breast cancer cells and clinical tumor samples, and other remaining subpopulations (CD44+/CD24+, CD44−/CD24+, CD44−/CD24−) were termed as non-BCSCs." (PMID 33934099, 2021). "In breast cancer, CD24−/CD44+ CSCs were evaluated by flow cytometry before and after treatment only in a neoadjuvant trial where, similar to our study, a proportion of patients showed no detectable CD24−/CD44+ at baseline." (PMID 31924241, 2020). "We also compared the expression levels of miR-29a in 12 pairs of human breast cancer tissues and their corresponding distal non-cancerous tissues, and in a more aggressive breast cancer cell line, MDA-MB-231 cells, which contains high ratio of CD44+/CD24− cells (~80%)." (PMID 30792382, 2019). "Flow cytometry data showed that CXCL1 treatment did not increase CD44+/CD24- or aldehyde dehydrogenase assays (ALDH+) in the MDA-MB-231 and MCF-7 breast cancer cell lines, indicating that CSC-enhancing effects may not explain CXCL1-induced metastasis." (PMID 30158589, 2018).